TRAF6 (TNF receptor associated factor 6)
Diseases named in the same sentence as TRAF6 in open-access papers (continued):
Sharing a sentence is not in itself a finding about the gene and the disease.
colorectal cancer (continued). "TRAF6 directly interacts with RIPK1 through the polyubiquitination of Lys48-linked RIPK1 and reduces the levels of RIPK1 protein in colorectal cancer cells, leading to necroptosis, thus promoting the proliferation of colorectal cancer cells." (PMID 36604411, 2023). "We showed by electron microscopy that colorectal cancer cells with low expression can show significant necroptosis compared with high expression of TRAF6 cells." (PMID 36604411, 2023). "TRAF6 is expressed and distributed in a variety of malignant tumor tissues, including colorectal cancer tissues." (PMID 35935327, 2022). "The expression of chemokine CCL3 and receptor CCR5 is positively correlated with the expression of TRAF6 and NF-κB and can promote the proliferation, invasion, and migration of colorectal cancer through TRAF6 and NF-κB pathway." (PMID 35935327, 2022). "In cancer, TRAF6 has been uncovered to work as a tumor-promoter in colorectal cancer, oral cancer, pancreatic cancer, prostate cancer and so on." (PMID 33061856, 2020). "TRAF6 promotes the progression of colorectal cancer both in vitro and in vivo through the AP-1 signaling pathway." (PMID 32905356, 2020). "miR-124 has also been reported to be related to negative regulation of TRAF6 expression in human osteosarcoma cells and colorectal cancer cells." (PMID 32905356, 2020). "Overexpression of TRAF6 predicts a poor response to chemotherapy and radiotherapy for colorectal cancer patients, with molecular studies suggesting this is because TRAF6 regulates mitochondrial translocation of p538." (PMID 29176576, 2017). "Moreover, Desulfovibrio vulgaris flagellin exacerbates colorectal cancer epithelial–mesenchymal transition via LRRC19/TRAF6/TAK1 signaling pathway activation, promoting tumor growth." (PMID 41471248, 2025). "However, its role in colorectal cancer is controversial, especially since the regulatory mechanism of colorectal cancer necroptosis has not been studied, so it is of great significance to study the in-depth regulation of TRAF6 on colorectal cancer necroptosis." (PMID 36604411, 2023). "We performed western blotting experiments on colorectal cancer cells transiently and stably transfected with TRAF6 plasmids, and we found that the levels of RIPK1 and p-RIPK1 proteins in colorectal cancer cells that highly expressed TRAF6 protein were significantly reduced." (PMID 36604411, 2023). "However, the role of TRAF6 in colorectal cancer is still controversial, mainly because the specific regulatory mechanism of colorectal cancer is still unclear, and the death mode of colorectal cancer cells has not been elucidated." (PMID 36604411, 2023). "Therefore, we identified TRAF6 as a novel target molecule against necroptosis in colorectal cancer cells." (PMID 36604411, 2023). "For instance, TRAF6 (TNF receptor associated factor 6) promotes the interaction between LC3B and CTNNB1 through the ubiquitination of LC3B and promotes the selective autophagic degradation of CTNNB1, inhibiting colorectal cancer metastasis." (PMID 37740194, 2023). "We detected the death of colorectal cancer cells by overexpressing TRAF6 and knocking down TRAF6 protein expression levels and the results showed that high expression of TRAF6 could significantly inhibit the death of colorectal cancer cells." (PMID 36604411, 2023). "To confirm whether TRAF6 could induce tumor progression through the inhibition of necroptosis in colorectal cancer cells through the RIPK1-RIPK3-MLKL axis, we co-transfected TRAF6 and RIPK1 into SW480 cells." (PMID 36604411, 2023). "TRAF6 regulates the p38/c‐Jun pathway in diverse diseases, with effects including modulating inflammatory pathways in keratinocytes, promoting cell proliferation and progression in colorectal cancer, and inducing angiogenesis." (PMID 37484971, 2023). "Therefore, we can infer that TRAF6 inhibits the necroptosis of colorectal cancer cells by inhibiting the RIPK1-RIPK3-MLKL signaling pathway." (PMID 36604411, 2023).
colorectal cancer (continued). "Therefore, our team further studied the role of TRAF6 in colorectal cancer, clarified its growth in colorectal tumors, and was the first to discover that it can increase its malignant biological behavior by regulating the way of cell death." (PMID 36604411, 2023). "Similarly, we performed western blotting experiments on colorectal cancer cells transiently transfected with Si-TRAF6 and stably transfected with Sh-TRAF6 plasmids." (PMID 36604411, 2023). "In this study, we confirmed that TRAF6 is highly expressed in colorectal cancer tissues." (PMID 35935327, 2022). "Therefore, the expression of important factors related to the CCL3–CCR5 axis and TRAF6/NF-κB pathway in colorectal cancer warrants further investigation." (PMID 35935327, 2022). "The expression of chemokine CCL3 and receptor CCR5 was positively correlated with the expression of TRAF6 and NF-κB and could promote the proliferation, invasion, and migration of colorectal cancer cells through TRAF6 and NF-κB." (PMID 35935327, 2022). "To observe the dynamics of NEMO puncta in the cytoplasm, we performed live cell imaging of NEMO and TRAF6 in the human colorectal carcinoma cell line HCT116 in which endogenous NEMO was knocked out by CRISPR and reconstituted with mCherry-tagged NEMO and green fluorescent protein (GFP) tagged TRAF6." (PMID 35477005, 2022). "In addition, STX2 has been reported to interact with TRAF6 to activate the NF-κB pathway in colorectal cancer cell lines." (PMID 34295885, 2021). "In addition, it has been reported that TRAF6 inhibits the transfer of colorectal cancer by regulating autophagy." (PMID 33456463, 2020). "The survival rate of colorectal cancer patients with high expression of TRAF6 is poor." (PMID 33294443, 2020). "To study whether tRXRα production and interaction with TRAF6 is clinic significant, we examined the expression of tRXRα in tissue specimens from patients with ulcerative colitis and colorectal cancer." (PMID 30931933, 2019). "Therefore, TRAF6 has been proposed as a prognostic indicator for colorectal cancer." (PMID 38169510, 2024). "Therefore, we could confirm that TRAF6 in colorectal cancer cells induces tumor progression by inhibiting the RIPK1-RIPK3-MLKL necroptosis signaling axis." (PMID 36604411, 2023). "Meanwhile, TRAF6 regulates the abundance of RIPK1, inhibits RIPK1/RIPK3/MLKL necrosis signaling pathways and affects the progression of colorectal cancer." (PMID 38169510, 2024). "The study indicated that TRAF6 promoted the recognition and selective autophagic degradation of cis-acting circRNA generated by β-catenin (CTNNB1) by interacting with LC3 in colorectal cancer cell lines." (PMID 38016969, 2023). "In conclusion, we systematically confirmed the inhibitory effect of TRAF6 on the RIPK1-RIPK3-MLKL signaling axis in vivo and promoted the growth of colorectal cancer cells in a xenograft tumor model." (PMID 36604411, 2023). "This study used cell, tissue, and animal experiments to prove that CCL3 is highly expressed in colorectal cancer and confirmed that CCL3 can promote the proliferation of cancer cells, and its expression is closely related to TRAF6/NF-κB molecular pathway." (PMID 35935327, 2022). "In summary, our study demonstrates that KDM4B facilitates colorectal cancer growth and glucose metabolism by stimulating TRAF6-mediated AKT activation, implicating that KDM4B is a potential molecular target for colorectal cancer treatment." (PMID 31931846, 2020). "The recent study demonstrated that TRAF6 promotes colorectal cell progression by inhibiting the RIPK1/RIPK3/MLKL necroptosis signaling pathway, which may provide a new therapeutic target for colorectal cancer." (PMID 36604411, 2023).
osteopetrosis (32 papers, 2009 to 2026). Osteopetrosis, also known as marble bone disease, is a descriptive term that refers to a group of rare, heritable disorders of the skeleton characterized by increased bone density on radiographs. "Several years ago, inactivation of the TRAF6 gene inmice was shown to cause severe osteopetrosis, and morerecently, similar evidence was obtained in humans." (PMID 37465191, 2023). "TRAF6 is required for perinatal and postnatal survival of mice, and TRAF6 deficient (TRAF6−/−) mice develop osteopetrosis." (PMID 33498715, 2021). "TRAF6 is essential to osteoclastogenesis, and studies have demonstrated that TRAF6 is the only member of the TRAF family whose deficiency exhibits an osteopetrosis phenotype." (PMID 33802713, 2021). "TRAF6 is a pivotal component of the RANK signaling pathway, and Traf6-deficient mice exhibit severe osteopetrosis, defects in bone remodeling and tooth eruption caused by impaired osteoclast function." (PMID 31098335, 2019). "TRAF6 is especially important for RANK/RANKL signaling, as demonstrated by a study in which TRAF6-deficient mice developed osteopetrosis." (PMID 31382539, 2019). "TRAF6 knockout mice exhibit severe osteopetrosis with defects in bone remodeling caused by impaired osteoclast function." (PMID 26083531, 2015). "It was reported that TRAF6-deficient mice develop osteopetrosis with defects in bone remodeling caused by impaired osteoclast formation." (PMID 23762085, 2013). "TRAF6-deficient mice exhibit severe osteopetrosis, and are defective in bone remodeling caused by impaired osteoclast function." (PMID 23536866, 2013). "TRAF6-deficient mice develop osteopetrosis and occlusion of the bone marrow (BM) cavities from a lack of osteoclast function." (PMID 19270748, 2009). "Traf6 knockout (KO) in mice resulted in osteoclast deficiency and osteopetrosis, which indicates that the regulation of TRAF6 could be the direction for osteoporosis therapy." (PMID 39536082, 2024). "Therefore, TRAF6 is a crucial factor for OCs formation and activation, as shown in a study on mice with inactivating mutation of TRAF6 (TRAF6-/-) with severe osteopetrosis." (PMID 36769345, 2023). "In addition to cytokine production, RANKL-induced signaling in macrophages and osteoclastogenesis are also controlled by TRAF6 since TRAF6-deficient mice display osteopetrosis due to an osteoclast defect." (PMID 36911671, 2023). "Furthermore, TRAF6-deficient mice also exhibit defects in the osteoclast differentiation and functions, leading to osteopetrosis phenotypes." (PMID 24961988, 2014). "Two reports using TRAF6 deficient mice indicated osteopetrosis-like symptoms in both." (PMID 23762085, 2013). "RANK-mediated activation of NF-κB is indispensable for osteoclast formation in vitro, and disruption of TRAF6, an essential adaptor in this pathway, leads to severe osteopetrosis 51–57." (PMID 41559024, 2026). "Disruption of RANK, RANKL, or TRAF6 in mice results in severe osteopetrosis, confirming the indispensability of this pathway in skeletal homeostasis." (PMID 41559024, 2026). "RANK interaction with TRAF6 is essential for RANKL signaling in osteoclasts as TRAF6-/- mice show severe osteopetrosis." (PMID 35463988, 2022). "Atypical cases of osteopetrosis have been reported in two siblings affected by severe combined immunodeficiency (SCID), who carry a mutation in the TNF receptor-associated factor 6 (TRAF6) gene, the most important adaptor for the RANK/RANKL signaling pathway." (PMID 33970241, 2021). "Among TRAF family members, TRAF6 is the most important and indispensable factor for osteoclast development, as a Traf6 knockout generates a severe osteopetrosis phenotype in mice due to the inability of osteoclast precursors to form functional osteoclasts." (PMID 32121289, 2020). "TRAF6-knockout mice displayed a defect in NF-κB signaling and consequently developed osteopetrosis, indicating the essential role of TRAF6 in osteoclast function." (PMID 30692521, 2019).
osteopetrosis (continued). "Evidence supporting the fact that TRAF-6 is a key protein in osteoclastogenesis was obtained from TRAF-6 knockout mice that developed osteopetrosis." (PMID 26347587, 2015). "In vivo evaluation of the genetic deficiency in TRAF6 confirmed its role in CD40-, IL-1-, and LPS signaling and phenotypically resulted in severe osteopetrosis." (PMID 20644648, 2010). "TRAF6-knockout mice displayed a defect in NF-κB signaling and consequently developed osteopetrosis." (PMID 37675145, 2023). "TRAF6-deficient mice were used to examine the role of TRAF6 for RANKL-induced osteoclast formation; these mice exhibited reduced numbers of osteoclasts and osteopetrosis symptoms." (PMID 35163403, 2022). "TRAF-6 and Src knockout mice develop osteopetrosis due to impaired bone resorption by osteoclasts." (PMID 34572081, 2021). "TRAF6 null mice develop severe osteopetrosis, spleen enlargement, hepatomegaly, and cardiomegaly." (PMID 31635168, 2019). "The significance of TRAF6 in the maintenance of normal bone architecture was demonstrated in TRAF6 knockout mice, which displayed a defect in NF-κB signaling and consequently developed osteopetrosis." (PMID 22719861, 2012). "TRAF6-ΔB mice were born at the expected Mendelian ratio and exhibited normal growth rates, without inflammatory lesions or osteopetrosis." (PMID 19270748, 2009).
colitis (31 papers, 2013 to 2025). Inflammation of the colon. "ASB3 is associated with dysregulation of the colitis microbiota and promotes proinflammatory factors’ production by disrupting TRAF6 stability." (PMID 39162488, 2024). "A functional analysis revealed that ARC suppressed the ubiquitination of TRAF6 by directly interacting with it, thereby activating the NF-κB pathway in T cells and subsequently resulting in the suppression of colitis-associated carcinogenesis." (PMID 39351758, 2024). "Previous studies have shown that injection of TRAF6 siRNA can reduce neuropathic pain and inflammatory pain behavior by reducing the inflammatory response caused by spinal nerve ligation or neonatal colitis." (PMID 36550542, 2022). "Next, we explored the therapeutic potential of targeting both RIPK2 and TRAF6 in colitis and colitis-associated CRC." (PMID 33893298, 2021). "Extracellular vesicles containing miR-146a ameliorates experimental TNBS caused colitis by targeting TRAF6 and IRAK139." (PMID 32733020, 2020). "The defective suppression activity of TRAF6-deficient Tregs was confirmed through the failure to suppress colitis in Rag2-/- mice by the co-transfer of naïve T cells and Tregs." (PMID 24058613, 2013). "In DSS-induced colitis, the mRNA expression of NF-κB, MyD88, and TRAF6 was elevated (p < 0.05), while the expression of p-p65 was significantly up-regulated in the colons of mice in the DSS group (p < 0.01)." (PMID 40130239, 2025). "For instance, BMSCs transfected with lentiviruses to overexpress miR-146a were found to significantly suppress inflammation by downregulating TNF receptor-associated factor 6 (TRAF6) and IL-1 receptor-associated kinase 1 (IRAK1) in colitis models." (PMID 39610953, 2025). "ARC repressed colitis-correlated tumorigenesis by activating the NF-κB pathway in T cells via inhibiting the ubiquitination of TRAF6." (PMID 39351758, 2024). "Confocal immunostaining showed that the colocalization between LRRC19 and TRAF6 in DVF-treated colitis mice was highly visible, but colocalization of LRRC19 and TRAF2 was rarely observed." (PMID 38172943, 2024). "It was showed that these obtained EV significantly inhibited TNF receptor-associated factor 6 (TRAF6) and IL-1 receptor-associated kinase 1 (IRAK1) expression in TNBS-induced colitis of rats." (PMID 36012170, 2022). "We found that the combination of both RIPK2 and TRAF6 inhibitors appeared to synergistically ameliorate colitis." (PMID 33893298, 2021). "Studies about Inflammatory bowel disease (IBD) showed that overexpressing miR-146a inhibited TNF receptor-associated factor 6 (TRAF6) and IL-1 receptor-associated kinase 1 (IRAK1) expression in TNBS-induced colitis of rats." (PMID 32483483, 2020). "While one study reports the colitis development in mice due to deletion of TRAF6 from intestinal epithelial cells, another study reports a higher TRAF6 expression in the colonic mucosa of UC and CD patients as compared to the non-IBD individuals." (PMID 32039213, 2019). "The contribution of TRAF6 in colitis development has been explored earlier, but the results are not conclusive." (PMID 32039213, 2019). "Although TRAF-6-knockout Tregs had similar inhibitory activity to wild-type Tregs in vitro, the reduced number of Foxp3-positive cells suggests that TRAF-6 knockout cannot suppress the development of colitis in mice with lymphopenia." (PMID 28219358, 2017). "Other studies have reported that hyperalgesia owing to central sensitization via TRAF6/nuclear factor-κB (NF-κB) was observed in visceral pain models, as knockdown of TRAF6 suppressed colitis-induced activation of NF-κB and increased TNF-α and IL-1β in the spinal cord." (PMID 39044893, 2024). "In addition, TRAF3 has been shown to be a negative regulator of inflammation in the TNBS-induced colitis mouse model by interfering with IL-17/IL-17R/Act1/TRAF6-mediated proinflammatory pathways though binding to IL-17R." (PMID 34956195, 2021).
colitis (continued). "Although TRAF6-deficient Tregs possess similar in vitro suppression activity compared to wild-type Tregs, TRAF6-deficient Tregs did not suppress colitis in lymphopenic mice very efficiently due to reduced number of Foxp3-positive cells." (PMID 24058613, 2013). "In contrast, when naïve T cells were co-transferred with TRAF6-/-Tregs, Rag2-deficient mice showed colitis (naïve T+cKO Treg) like without Tregs (naïve T cell alone)." (PMID 24058613, 2013). "In conclusion, GLE supplementation promotes DSS-induced colitis recovery by regulating inflammatory cytokines, preserving the intestinal mucosal barrier, positively modulating microbiota changes, and positively influences immune response in TRAF6/MyD88/NF-κB signaling pathways." (PMID 36553765, 2022). "Similarly, specific knockout of TRAF6 in IECs also leads to severe DSS-induced colitis in mice, suggesting that TRAF6 exhibits protective anti-inflammatory effect in intestinal epithelial cells; it is worth noting that this effect appears to be independent of TLR signals." (PMID 34956195, 2021). "Furthermore, MDP‐induced IRF4 inhibits polyubiquitination of TRAF6 and RICK, thereby reducing NF‐κB expression in a TNBS‐induced colitis model." (PMID 37341064, 2023). "For instance, EVs containing miR‐146a could target TRAF6 and IRAK1 to ameliorate experimental colitis." (PMID 35582765, 2022). "Mice lacking TRAF6 in intestinal epithelial cells (IECs) (Villin-Cre Traf6flox/flox) show an exacerbated phenotype in DSS colitis: a model for intestinal bowel diseases." (PMID 31156649, 2019). "TRAF6 signaling independent of TLRs likely limits DSS-induced colitis not by mediating intrinsic functions involved in IEC homeostasis, but instead by inducing the release of epithelial cytokines such as TGF-β to exert direct or indirect anti-inflammatory functions." (PMID 39162488, 2024). "In a mouse model of colitis induced by dextran sodium sulfate, LRRK2 lies downstream of the β-glucan receptor Dectin-1 and overexpression of LRRK2 leads to the activation of the NF-κB components, TAK1 complex and TRAF6, and the enhancement of pro-inflammatory cytokine secretion." (PMID 36972292, 2023). "Given that segmental changes can exhibit inflammation in the colon in IBD patients and that intestinal segments in endoscopic remission can appear as histologic colitis, we determined the expressions of TRAF4 and TRAF6 both in inflamed and non-inflamed intestinal mucosae." (PMID 23431243, 2013).